PXN (paxillin)
Diseases named in the same sentence as PXN in open-access papers (continued):
Sharing a sentence is not in itself a finding about the gene and the disease.
tumor (178 papers, 2008 to 2025). "Among these, elevated mRNA and paxillin levels have been associated with histological tumor grade, tumor size, clinical TNM stage, and distant metastases." (PMID 40310348, 2025). "The dysregulated activation of the PI3K/Akt pathway by paxillin is frequently associated with enhanced invasiveness in tumor cells." (PMID 40001476, 2025). "In gliomas, paxillin overexpression is significantly associated with poor prognosis, mainly by promoting tumour cell proliferation and invasion." (PMID 40045379, 2025). "Impressively, a treatment with the phytopharmaceutical causes a concentration-dependent inhibition of tumor marker paxillin and simultaneously an enhanced E-cadherin-containing plaque deposition in HCT-116 and RKO cells." (PMID 38190940, 2024). "The major cause of cancer cell migration, invasion, and metastasis is loss of adhesion to the ECM, and PXN has a key role in the tumor formation, progression, invasion, and metastasis." (PMID 38962075, 2024). "In an FGFR independent manner, incubation with soluble NCAM or loss of polySia attenuates tumor cell migration and augments the number of focal adhesions by enhancing the association between p59Fyn with the focal adhesion scaffolding protein paxillin." (PMID 39420834, 2024). "It has been shown that PXN is involved in several types of cancers and strong PXN expression causes accelerated tumor cell proliferation, invasion, migration, and aggressiveness." (PMID 38962075, 2024). "The immunohistochemical expression of FAK, Src and paxillin proteins in formalin-fixed paraffin-embedded tumour tissue was analysed in association with various clinicopathological features." (PMID 39036223, 2024). "As integrin/FAK/paxillin has been reported to cause tumor migration and invasion, we next examined these modulated cell migration-related protein expressions by western blotting." (PMID 36672499, 2023). "Although paxillin mutations in somatic cells are rare, studies have also shown that paxillin mutations are associated with tumor progression." (PMID 37175948, 2023). "Overall, there is a consistent conclusion that can be made: aberrant paxillin expression is associated with clinical tumor prognosis, proliferation, invasion, and metastasis." (PMID 37175948, 2023). "Paxillin phosphorylation is critical in determining a cell’s ability to migrate and hence has been linked to processes such as wound repair and tumor metastasis." (PMID 32079527, 2020). "The most recent study shows that accumulation of paxillin in autophagy-deficient tumor cells impairs migration ability of motile cells, and co-localization of paxillin with autophagosome indicates paxillin is degraded by autophagy." (PMID 30200999, 2018). "Both MAPK and FAK/paxillin pathways are associated with tumor progression, migration, invasion, and metastasis in many types of tumors." (PMID 28423510, 2017). "EGF, TGF-β, platelet derived growth factor (PDGF) and androgen receptor mediated signaling are all known to induce paxillin phosphorylation, an event linked to tumor growth and metastasis." (PMID 26980710, 2016). "Two identified JNK targets in scrib- + RasACT tumours are the matrix metalloproteinase protein, Mmp1 [our unpublished observations,], and the integrin-associated scaffolding protein, Paxillin (this study)." (PMID 19778415, 2009). "Paxillin upregulation in tumor cells is closely linked to invasiveness and metastasis." (PMID 40001476, 2025). "In addition, focal adhesion proteins such as integrin, FAK, Src, paxillin and zyxin have also been found to be present in tumours in a variety of mutated forms, and these mutations play an important role in tumourigenesis and progression." (PMID 40045379, 2025). "The higher likelihood of Src expression in stage T3 and paxillin expression in stage T3 and grades 3-4 may imply their role in progression to more advanced stages, or it may be associated with a more aggressive tumour profile." (PMID 39036223, 2024).
tumor (continued). "The aberrant expression of paxillin is often associated with carcinogenesis and is associated with poor tumor prognosis, so the assessment of paxillin expression may provide some promising value in the prognosis of cancer." (PMID 37175948, 2023). "The LUAD upregulation of PXN is associated with tumor progression and metastasis." (PMID 36675528, 2023). "Furthermore, PODXL knockdown cells exhibit significantly diminished tumour migration, invasion, as well as proliferation and colony formation, indicating that PODXL expression is associated with tumour aggression through FAK/paxillin/cortactin signalling." (PMID 34201212, 2021). "Moreover, we also detected a correlation between PXN expression and tumor-infiltrating immune cells in cancer-associated fibroblasts." (PMID 34135128, 2021). "This complex phosphorylates a fraction of paxillin specifically associated with the cell membrane, and promotes Rac1 activation, thereby triggering membrane ruffling and cell invasion in both normal fibroblasts and tumor cells." (PMID 30459815, 2018). "This complex phosphorylates a fraction of paxillin specifically associated to the cell membrane, and promotes Rac1 activation, thereby triggering membrane ruffling and cell invasion in both normal fibroblasts and tumour cells." (PMID 27181366, 2016). "We found that on both substrates, FAK were detected in Bit1 immunoprecipitations, meanwhile, Bit1 was detected in FAK immunoprecipitations It is well documented that FAK and Paxillin is tightly associated with tumor progression, migration, invasion and metastasis in many tumors." (PMID 26956728, 2016). "Overexpression of PXN is associated with aggressive tumor phenotypes and adverse overall survival, thus implicating PXN might serve as an useful prognostic indicator." (PMID 24180516, 2013). "Positive ezrin and paxillin protein expression was seen in 99% and 93.7%, respectively, of urothelial tumors; downregulation of ezrin and paxillin in urothelial bladder tumors was associated with aggressive tumor features and invasiveness." (PMID 23209815, 2012). "In the cultured SCC-5, they found a strong association of PXN expression with the increased chemoresistance, proliferation rate, migration, and invasion potential of side population (SP) cells, which had been previously shown to be responsible for tumor relapse." (PMID 38962075, 2024). "Integrin beta 4 (ITGB4) forms a critical link between the extracellular matrix and the cell interior by interacting with focal adhesion via paxillin, and its presence in tumor-derived exosomes facilitates the creation of a microenvironment that promotes LC." (PMID 41440381, 2025). "In clinical specimens of HNSCC, the overexpression of PXN mediated by HPV E6 drives tumor progression and correlates with inferior disease-free survival, recurrence-free survival, and overall survival rates." (PMID 40821990, 2025). "For apoptosis and survival, paxillin is a known modulator of tumor cell survival, particularly through the PI3K/Akt and ERK/MAPK pathways." (PMID 40001476, 2025). "The cooperation between paxillin and kindlin in integrin activation and focal adhesion dynamics offers valuable insights into tumor metastasis, immune function, and tissue repair." (PMID 40001476, 2025). "Paxillin plays a pivotal role in regulating cellular adhesion and signaling across various cell types, including epitheliumfibroblasts, immunocyte, and tumor cells, with unique mechanisms tailored to each context." (PMID 40001476, 2025). "In the tumor microenvironment, paxillin and kindlin play pivotal roles by interacting with integrins to regulate cellular responses to the ECM." (PMID 40001476, 2025). "Increased paxillin levels enhance tumor cell proliferation, migration, and invasion by activating key signaling cascades, notably the PI3K/Akt and MAPK pathways." (PMID 40001476, 2025).
tumor (continued). "PLA studies further confirmed the presence of FAK–paxillin complexes at the leading edge of durotaxing PDAC3 tumour cells (QM phenotype)." (PMID 40925952, 2025). "It has been reported that paxillin knockdown suppresses EMT during tumor progression and metastasis." (PMID 39991922, 2025). "Paxillin plays a critical role in tumor metastasis by facilitating cell detachment, migration, and invasion through its interaction with FAK and Src." (PMID 40001476, 2025). "The phosphorylation of paxillin is crucial for enabling tumor cell migration and invasion, highlighting its role as an oncogenic factor in various malignancies." (PMID 40001476, 2025). "In cancers from the breast, lung, and colon, paxillin overexpression enhances tumor cell adhesion to the ECM, promoting migration and invasion." (PMID 40001476, 2025). "Functionally, ephrin-B1 modulates multiple pathways, including p38, MSK1/2, Stat1/2/4/5a/6, and paxillin, following ligand stimulation or EphB2 inhibition, suggesting broad influence over tumor behavior." (PMID 41200151, 2025). "Consistent with previous results, A5-LNP-DOX treatment significantly suppressed tumor growth and reduced PXN expression, cell proliferation, and microvessel density." (PMID 40634277, 2025). "Autophagy promotes focal adhesion disassembly and cell motility of metastatic tumor cells through the direct interaction of PXN (paxillin) with LC3." (PMID 40097917, 2025). "Several studies have shown that PXN is a factor in tumor formation, progression, invasion, and metastasis." (PMID 38962075, 2024). "PXN, a cytoskeletal protein, when overexpressed, facilitated tumor progression and acted as an oncogene by regulating Bcl-2." (PMID 38183097, 2024). "The correlation between aberrant paxillin expression in cancer patients and unfavourable clinical outcomes, such as poor prognosis, tumour occurrence, and metastasis, further underscores its significance as a potential prognostic marker and therapeutic target." (PMID 38500921, 2024). "Overall, this review highlights the role of the abnormal expression of paxillin in tumor progression and related molecular mechanisms, as well as the potential for paxillin to be used in tumor therapy." (PMID 37175948, 2023). "It has been demonstrated that Paxillin plays an important role in tumor metastasis, which can recruit signaling molecules involved in cell movement and adhesion." (PMID 36732762, 2023). "The signal transducer and activator of transcription 3 (STAT3) act as a marker of tumor angiogenesis, interacting with Src and forming a complex with paxillin." (PMID 37175948, 2023). "Targeting of the CCR4-phospho-paxillin axis was sufficient to reduce tumor progression and neuro-affinity of cancer cells in vivo." (PMID 37607005, 2023). "SEPT11 activates FAK/Src/paxillin pathway and thus promotes tumor migration, but both Rhosin and Y27632 can significantly inhibit the activation of this signal pathway by SEPT11." (PMID 37080972, 2023). "Paxillin is a multifunctional cytoskeletal protein that is involved in cell adhesion and highly phosphorylated in the tumor tissues and cells." (PMID 36732762, 2023). "Previous studies have revealed the important role of the simultaneous phosphorylation of multiple tyrosine sites of paxillin in facilitating tumor cell migration and invasion." (PMID 37958964, 2023). "Herein, we review the structure of paxillin and its function and expression in tumors, paying special attention to the multifaceted effects of paxillin on tumors, the mechanism of tumorigenesis and progression, and its potential role in tumor therapy." (PMID 37175948, 2023). "miR-212 acts as an epigenetically silenced tumor suppressor to suppress migration and invasion phenotypes of GC cell lines by downregulating paxillin expression." (PMID 37175948, 2023). "Compared with paxillin alone, the combination of paxillin and other tumor markers can be a better choice for tumor prognosis." (PMID 37175948, 2023).
tumor (continued). "Consistent with the data from cultured cells, immunoblotting assays demonstrated the regulatory effect of miR‐503 on PTK7, FAK, and paxillin in mouse tumor tissues." (PMID 37212485, 2023). "PXN expression presented a superior ability in predicting long-term survival compared with age and tumor residual disease." (PMID 36923874, 2023). "VEGF receptor 2 (VEGFR2) acts as a major signal transducer in VEGF-regulated angiogenesis, and the inhibition of VEGF/VEGFR2/FAK/paxillin signaling inhibits tumor angiogenesis." (PMID 37175948, 2023). "A better understanding of the functional mechanism of paxillin will help us to understand tumor survival and metastasis processes and provide valuable opportunities for tumor therapeutic intervention in the future." (PMID 37175948, 2023). "Tumor-secreted vascular endothelial growth factor (VEGF) increases capillary endothelial cell ingrowth by reducing paxillin expression to inhibit NRP2 expression in vitro and in vivo while stimulating the formation of new functional microvessels in vivo." (PMID 37175948, 2023). "FAK also regulates tumor angiogenesis and cell survival by forming complexes with phosphorylated paxillin and Src." (PMID 37175948, 2023). "Many pathways are involved in the development of different stages of tumors, and many studies have also shown that paxillin participates in and activates a variety of signaling pathways to affect tumor progression." (PMID 37175948, 2023). "Our recent work showed that NSCLC tumor tissue has the heterogenous expression of PXN/ITGB4, and patients with the increased expression of both these genes have poor overall survival." (PMID 36675528, 2023). "Paxillin deficiency leads to the mislocalization of Src-activated STAT3, while STAT3 activity upregulates VEGF expression to promote tumor angiogenesis." (PMID 37175948, 2023). "PXN promoted tumor progression and predicted survival and relapse in oral cavity squamous cell carcinoma." (PMID 36923874, 2023). "Some other potential tumor therapeutic compounds can play a certain role in tumor therapy by targeting paxillin and its signaling pathway." (PMID 37175948, 2023). "We found TGF-α content of the primary tumor, and p-paxillin in cancer cells within samples from patients with PDAC to be unfavorable prognostic markers for overall survival." (PMID 37607005, 2023). "Then, the distribution of age, grade, tumor residual disease, stage, and lymphatic invasion in low and high PXN expression groups was evaluated using the chi-square test." (PMID 36923874, 2023). "A growing body of research is supplementing our understanding of the potential role of aberrant paxillin expression in tumor cells and its impact on tumor malignant progression." (PMID 37175948, 2023). "Paxillin is a critical protein that mediates signaling between tumor microenvironment and tumor cells and influences tumor metastasis." (PMID 35918694, 2022). "PXN, also known as paxillin, is a focal adhesion protein, which sends signals from the extracellular matrix, and promotes tumor cell proliferation." (PMID 35222428, 2022). "The results of pan-cancer analysis showed that abnormal PXN expression was related to poor prognosis, immune infiltration, and protein phosphorylation in different tumor types." (PMID 34135128, 2021). "The data showed that ECM1b inhibited the phosphorylation of AKT/FAK/Paxillin/Rac and the tumor growth of cells in animals." (PMID 34244494, 2021). "We used the dataset from TCGA and GEPIA to investigate the correlation of PXN expression with prognoses of patients across different tumor types." (PMID 34135128, 2021). "Up-regulated autophagy facilitates tumor metastasis by degrading paxillin, which disassembles focal adhesions and promotes tumor mobility 10-12." (PMID 34522207, 2021). "PXN is related to cancer cell movement, migration, and invasion and ultimately shows a certain correlation with tumor metastasis." (PMID 34424263, 2021).
tumor (continued). "The high expression of PXN in certain tumors is related to tumor stage, poor differentiation, lymphatic vascular invasion, lymphatic metastasis, distant metastasis, tumor lymph node metastasis staging, and recurrence in distant sites after radical surgery." (PMID 34135128, 2021). "In tumors derived from the injection of catulin reporter cell lines, a strong expression level of PXN was visible at the tumor invasion front, co-localizing with catulin-GFP expression." (PMID 35008571, 2021). "Compared with parental cells or vector-transfected control cells, cells transfected with ECM1b or ECM1a exhibited reduced or enhanced phosphorylated AKT/FAK/Paxillin/Myosin protein levels and xenograft tumor development, respectively." (PMID 34244494, 2021). "Strikingly, further analysis of data within the TCGA database demonstrates significantly higher FAK (PTK), Pyk2 (PTK2B), and paxillin (PAX) mRNA in tumor samples compared to normal." (PMID 34031486, 2021). "Overexpression of CHD1L transcriptionally suppressed the expression of autophagy inhibitor ZKSCAN3, and accelerated autophagic degradation of Paxillin, which is crucial for dynamic disassembly of FA of tumor cells." (PMID 34654797, 2021). "PXN was discovered by searching for oncogenic target genes of miR-199-5p and miR-199-3p, tumor suppressive miRNAs in HNSCC." (PMID 34946859, 2021). "Mutation of the GPR motif in ECM1a to VAQ eliminated the ability of ECM1a to bind to integrin αXβ2, activate AKT/FAK/Paxillin/Rac signaling and induce tumor growth." (PMID 34244494, 2021). "The differential expression of PXN in different tumor types suggested that PXN has various regulatory mechanisms in different tumor types." (PMID 34135128, 2021). "The human PXN gene has four isoforms, and the outcome of alternative splicing, and the gene exerts important roles in focal adhesion, tumor progression and migration, barrier dysfunction of endothelial cells, inflammation, and oxidative stress." (PMID 34135128, 2021). "CQ has been reported to reduce the degradation of paxillin, which supports anchoring of tumor cells to the primary tumor lesion, and prevents the first crucial step of metastasis." (PMID 34690764, 2021). "Another adhesion component that can influence tumour growth by affecting both vessel formation and permeability, is paxillin." (PMID 33573141, 2021). "Western blots of PANC-1 tumor protein extracts that were reacted with an antibody to phospho-paxillin were decreased in tumors of mice treated with the combination therapy." (PMID 34638432, 2021). "It has been proved that paxillin involves in the regulation of the cytoskeleton, tumor invasion, and metastases." (PMID 34268882, 2021). "Next, we used the CPTAC dataset to study the protein level of PXN between different tumor types and normal tissues." (PMID 34135128, 2021). "To support a correlation of PXN expression levels between tumor and normal tissues, we used GEPIA2, which analyzed our target genes from TCGA and in the GTEx projects." (PMID 34135128, 2021). "Inhibition of autophagy-dependent disassembly of focal adhesions maintains the attachment between paxillin in tumor cells and integrin on the ECM." (PMID 34690764, 2021). "In summary, we have identified a novel CHD1L/ZKSCAN3/Paxillin autophagic axis in regulating tumor cell migration and metastasis." (PMID 34654797, 2021). "The activation of the FAK-paxillin signaling pathway has been considered a crucial index for tumor metastasis." (PMID 33634070, 2021). "Herein, we demonstrated that ITGB1 enhanced HCC tumor progression via PXN/YWHAZ/AKT signaling pathways, which confers an increased growth ability to HCC tumors." (PMID 34977001, 2021).